PLCG2 (phospholipase C gamma 2)
Diseases named in the same sentence as PLCG2 in open-access papers (continued):
Sharing a sentence is not in itself a finding about the gene and the disease.
breast carcinoma (5 papers, 2014 to 2024). "This does not necessarily have to be true, although we identified polymorphisms in PLCG2 that had interactions with MHT use for both breast cancer risk and mammographic density." (PMID 26275715, 2015). "The functional role of PLCG2 in breast cancer has to be further elucidated before it is possible to derive a model that would explain our findings with PLCG2 variants." (PMID 26275715, 2015). "Indeed, PLCγ2 SNPs were identified as breast cancer risk factors in patients on menopausal hormone replacement therapy." (PMID 34157287, 2021). "However, three SNPs in PLCG2 showing potential interaction with MHT use for overall breast cancer risk in our previous study also showed potential interactions with MHT use for mammographic density in this study, but solely among cases." (PMID 26275715, 2015). "In other breast cancer cell lines, it signals via a Par2—phospholipase C γ2 (PLCγ2)—protein kinase C (PKC) pathway, resulting in the upregulation of NFkB and subsequent mmp9 expression responsible for metastasis." (PMID 37566613, 2023). "With regard to breast cancer, PLCG2 has been identified as an irradiation-responsive gene and a potential modifier of breast cancer risk in BRCA2-mutation carriers." (PMID 26275715, 2015).
cold urticaria (5 papers, 2013 to 2025). Cold urticaria is a condition that affects the skin. "PLAID with cold urticaria (CU-PLAID) is caused by in-frame deletions of PLCG2 that are dominant negative at physiologic temperatures but become spontaneously active at sub-physiologic temperatures." (PMID 38562814, 2024). "By identifying both the first de novo and splice site variants to cause PLCG2-associated immune dysregulation with cold urticaria (CU-PLAID), we demonstrate the diagnostic utility of PLCG2-specific RNA-sequencing." (PMID 38562814, 2024).
COVID-19 (5 papers, 2022 to 2024). A disease caused by infection with severe acute respiratory syndrome coronavirus 2. "Cardiac injury due to COVID-19-induced differential expression of PLCG2 in cardiomyocytes may be associated with myocarditis." (PMID 37109540, 2023). "The expression of PLCG2 transcripts is upregulated in club cells after SARS-CoV-2 infection, and PLCG2 is highly expressed in the kidneys of patients with COVID-19." (PMID 37109540, 2023). "Specifically, we found a set of 89 DE genes in COVID-19 macrophages from all three organs, including PLCG2, HIF1A, ACTB, and JUND." (PMID 37830426, 2023). "Recent publications have provided evidence of the differential expression of PLCG2 after COVID-19 vaccination." (PMID 36936955, 2023). "Another 2022 study found no elevated anti-S1 IgA levels in a subject carrying a mutation in the PLCG2 gene after a booster dose of BNT vaccine, suggesting a role of PLCG2 after COVID-19 vaccination." (PMID 36936955, 2023). "PLCG2 expression in CD8+ T cells may represent T cell immunological response following COVID-19 vaccination." (PMID 36936955, 2023). "Therefore, the expression of PLCG2 is altered after COVID-19 vaccine administration." (PMID 36936955, 2023). "Although no direct evidence of COVID-19 vaccination has been reported, changes in PLCG2 expression after infection with SARS-CoV-2 partially demonstrate the effectiveness of PLCG2 as a feature." (PMID 36936955, 2023).
soft tissue sarcoma (5 papers, 2021 to 2024). A malignant neoplasm arising from muscle tissue, adipose tissue, blood vessels, fibrous tissue, or other supportive tissues excluding the bones. "In recent years, clinical researchers have identified PLCG2 as a tumor microenvironment (TME)-related gene in soft tissue sarcoma." (PMID 37074454, 2023). "In a bioinformatics analysis of the tumour microenvironment in soft tissue sarcoma, PLCG2 was found to be an indicator of the tumour microenvironment and patient prognosis." (PMID 37226082, 2023). "Thus, in solid colon tumors and soft tissue sarcoma, PLCG2 gene expression positively correlates with immune cell infiltration into the tumor microenvironment and favorable prognosis, while PLCG2 gene mutations produce resistance of some tumors to chemotherapy." (PMID 37509254, 2023).
Allergy (4 papers, 2021 to 2025). An allergy is an immune response or reaction to substances that are usually not harmful. "The highest prevalence of allergy was found in patients suffering from genetic disorders caused by variants in DOCK8, CARD11 (AD DN), ARPC1B, and PLCG2, while there were no occurrences of allergy in patients with defects in the LRBA and RAG1 genes." (PMID 41142799, 2025). "While the IUIS 2022 classification report states that allergy or atopy is characteristic for these conditions, it does not do so for ARPC1B, PLCG2, and IL6ST deficiencies – all of which had a high prevalence of allergy in our study." (PMID 41142799, 2025).
cognitive decline (4 papers, 2020 to 2025). "This includes the effect described here for the APOE-ε4 allele and p.P522R in PLCG2 on the cognitive decline." (PMID 32166339, 2020). "In this study, we provide the first evidence linking the protective effect of the p.P522R variant in PLCG2 with a slower cognitive decline in patients with MCI and reduced pTau181 and tTau levels." (PMID 32166339, 2020). "Genome-wide association studies identified a mutation within the phospholipase C gamma 2 (PLCG2) gene, called P522R, that protects against AD-related cognitive decline." (PMID 39487477, 2024). "A study conducted by Kleineidam and colleagues found that Tau can bind to the SH3 domain of PLCγ2 and that P522R, a protective variant of PLCG2, can reduce p-Tau levels in cerebrospinal fluid and delay cognitive decline in individuals with MCI." (PMID 36147734, 2022). "In line with this hypothesis, we observed no protective effect of the PLCG2 variant on the cognitive decline in population-based studies probably due to the lower prevalence of amyloid positivity in these samples compared to MCI patients." (PMID 32166339, 2020). "To directly compare the protective effect of PLCG2 with that of APOE, we expressed the APOE effect on cognitive decline in protective terms, i.e., cognitive changes when APOE-ε4 is absent." (PMID 32166339, 2020). "Furthermore, the rate of cognitive decline was reduced in patients with mild cognitive impairment carrying the PLCγ2-P522R variant compared to those not carrying the variant, suggesting that the PLCγ2-P522R variant has universally beneficial effects on cognition and brain health upon aging." (PMID 40038760, 2025).
colon cancer (4 papers, 2021 to 2024). "As shown in the interaction network, immune-related gene PLCG2 and IGF1, which are up-regulated in colon tumor samples, have significantly strong correlation with several TFs: FOXP3, IKZF1, CBX7, LMO2, MEF2C, EPAS1 and MAF." (PMID 33996273, 2021).
dementia with Lewy bodies (4 papers, 2019 to 2021). "In this study, we addressed this knowledge gap by testing the association of ABI3_rs616338-T and PLCG2_rs72824905-G in purely autopsy-confirmed cohorts of 973 patients with Lewy body disease (LBD-NP) and 1040 with PSP, compared to 3351 controls." (PMID 33092647, 2020). "The AD protective R522 mutation in PLCG2, which also protects against dementia with Lewy bodies and FTD, appears to protect via increased PLCγ2 activity." (PMID 33841102, 2021).
familial cold autoinflammatory syndrome 3 (4 papers, 2016 to 2024). A rare, hereditary, immune deficiency with skin involvement characterized by early-onset cold urticaria after generalized exposure to cold air or evaporative cooling and not after contact with cold objects. "We also diagnosed two familial cold autoinflammatory syndrome 3 (FCAS3) caused by PLCG2 gain-of-function mutations." (PMID 33042144, 2020). "Mutations in the PLCG2 and NLRP3 genes cause familial cold autoinflammatory syndrome 3 and 1, respectively." (PMID 38177227, 2024).
urticaria (4 papers, 2022 to 2023). A vascular reaction of the skin characterized by erythema and wheal formation due to localized increase of vascular permeability. "Germline mutations in two different genes called PLCG2 and ADGRE2 which encode for Phospholipase C gamma 2 and Adhesion protein-coupled receptor E2 respectively, are associated with a type of urticaria triggered by cold and vibration." (PMID 37033173, 2023).
B cell lymphoma (3 papers, 2016 to 2022). "Here, we showed that HM71224 effectively blocked the phosphorylation of Btk and its downstream molecule, PLCγ2, in a human B cell lymphoma cell line and in primary human B cells following BCR activation." (PMID 27090981, 2016). "For B-cell lymphoma only three genes are found in cosmic (CD22, MDN1, and PlCG2) and three genes (CD22, PTPN6, PLCG2) are oncogenes." (PMID 34570764, 2021).
colorectal cancer (3 papers, 2012 to 2024). A primary or metastatic malignant neoplasm that affects the colon or rectum. "DNMT3B controls colorectal cancer cell proliferation through PLCG2, which is useful for developing therapeutic approaches that target PLCG2 expression for the treatment of colorectal cancer." (PMID 39108206, 2024). "Overexpression of PLCG2 effectively prevents the growth of colorectal cancer xenograft tumorsin vivo." (PMID 39108206, 2024). "Immunodeficient BALB/c mice harboring HCT116 cells stably transfected with either the vector or oePLCG2 lentivirus were used to investigate the role of PLCG2 in colorectal cancer carcinogenesisin vivo." (PMID 39108206, 2024). "The results showed stable expression of PLCG2 in normal tissues, whereas PLCG2 protein expression was decreased in colorectal cancer tissues." (PMID 39108206, 2024). "PLCG2 is identified as a key downstream regulatory protein of DNMT3B in colorectal cancer." (PMID 39108206, 2024).
cutis laxa (3 papers, 2018 to 2025). Cutis laxa (CL) is an inherited or acquired connective tissue disorder characterized by wrinkled, redundant and sagging inelastic skin associated with skeletal and developmental anomalies and, in some cases, with severe systemic involvement. "Here, we report a new patient with APLAID caused by a unique activating mutation in PLCγ2 that presented with novel manifestations, including cutis laxa and sensorineural deafness." (PMID 30619256, 2018). "In summary, our report shows that a novel heterozygous missense gain-of-function L848P mutation the PLCG2 gene causes APLAID in a patient who additionally presented cutis laxa which appears to extend the APLAID phenotype." (PMID 30619256, 2018). "These manifestations were initially vesicular and blistering lesions that subsequently evolved to the destruction of elastin fibers leading to large areas of cutis laxa in both patients, a phenomenon also described in the APLAID patient with the p.Leu848Pro PLCG2 variant." (PMID 32671674, 2020).
mantle cell lymphoma (3 papers, 2016 to 2025). Mantle cell lymphoma is a rare form of malignant non-Hodgkin lymphoma affecting B lymphocytes in the lymph nodes in a region called the ``mantle zone''. "Similarly, BTK plus PLCγ2 mutations, including mutations in the BTK amino acids L528, A428, and V416, were discovered in REC-1 mantle cell lymphoma (MCL) cell lines, which are resistant to vecabrutinib, pirtobrutinib, and fenebrutinib." (PMID 38469232, 2024).
nephrotic syndrome (3 papers, 2019 to 2024). A collection of symptoms that include severe edema, proteinuria, and hypoalbuminemia; it is indicative of renal dysfunction. "PLCγ2 missense coding variants have been identified as candidate loci in genome-wide association study of children with steroid-sensitive nephrotic syndrome." (PMID 38127456, 2024). "Recently, expression quantitative loci analysis of NS patients in the Nephrotic Syndrome Study Network (NEPTUNE) identified PLCG2 as one of the most highly regulated genes in the glomerulus, suggesting a possible role for PLCG2 modulation in NS." (PMID 30761277, 2019). "Human glomerular transcriptome data suggest that SH3BP2 recruits PLCG2 and VAV2 in downstream signaling in nephrotic syndrome." (PMID 38127456, 2024). "Immunofluorescence microscopy of Sh2bp2KI/KI mouse kidneys validated the importance of PLCγ2 and VAV2 downstream of SH3BP2 in nephrotic syndrome as suggested by in silico IMPRes analysis of human glomerular transcriptome." (PMID 38127456, 2024). "We used human transcriptomic and clinical data from the Nephrotic Syndrome Study Network (NEPTUNE) to demonstrate that SH3BP2, its partner molecules (especially PLCγ2 and VAV2), and innate immune signaling pathways are upregulated in the glomerular transcriptome in nephrotic syndrome." (PMID 38127456, 2024).
non-small cell lung carcinoma (3 papers, 2023 to 2025). A group of at least three distinct histological types of lung cancer, including non-small cell squamous cell carcinoma, adenocarcinoma, and large cell carcinoma. "High expression of PLCG2 is caused by the amplification of the PLCG2-encoding gene on EccDNA, and metastasis of non-small cell lung cancer is mediated by this high expression through enhanced mitochondrial respiration." (PMID 41210680, 2025). "In non-small cell lung cancer, PLCG2, an important oncogene and prognostic biomarker, was involved in tumor cell metastasis through the regulation of mitochondrial respiration." (PMID 39494327, 2024). "In non-small cell lung cancer (NSCLC), PLCG2 was correlated with HMGB1 expression and was a biomarker for predicting patient survival and progression." (PMID 39494327, 2024).
thrombotic disease (3 papers, 2017 to 2020). The formation of a blood clot in the lumen of a vessel or heart chamber; causes include coagulation disorders and vascular endothelial injury. "Since GPVI is an encouraging pharmacological target for the active and safe treatment of thrombotic diseases, inhibition of PLCγ2, PKC, and adenosine triphosphate (ATP) release are the major targets for the treatment of thrombotic diseases." (PMID 31163690, 2019). "Thus, inhibiting platelet NF-κB-mediated PLCγ2-PKC activation may have a high therapeutic potential to treat thrombotic disorders." (PMID 32646046, 2020).
viral infections (3 papers, 2015 to 2023). "Furthermore, 28 patients had viral infections, 19 of whom carried either CLEC7A or PLCG2 variants, compared with 9 without variants (n = 19 of 34 vs. 9 of 33; P = 0.0258, Fisher’s exact test)." (PMID 36166305, 2022).
cervical adenocarcinoma (2 papers, 2021 to 2024). An adenocarcinoma arising from the cervical epithelium. "PLCγ2 was also implicated in cervical adenocarcinoma, where in vitro siRNA knockdown of PLCγ2, and calmodulin 1, in human cervical adenocarcinoma cells led to an increased sensitivity to doxorubicin and paclitaxel, but not Cisplatin." (PMID 34157287, 2021).
Coronary arteriosclerosis (2 papers, 2022 to 2024). "ZEB2 and PLCG2 genes have shown stronger associations with coronary artery disease, with an association value>0.3." (PMID 35844366, 2022). "Coronary arteriosclerosis shared 10 GWS genes with AD (BAG6, C6orf10, HLA-DQB1, HLA-DRA, HLA-DRB1, NDUFAF6, NME7, PLCG2, PRRC2A, and TRIB1), while myocardial infarction shared three genes with AD (HLA-DRA, PHB, and RP11-81K2.1)." (PMID 39201500, 2024).
Fever (2 papers, 2019 to 2025). Body temperature elevated above the normal range. "Altogether, the patient history is more immediately related to a potential PLCG2 defect than to autoinflammatory periodic fever associated to abnormal function of TNFRSF1A." (PMID 32047491, 2019).
fungal infection (2 papers, 2018 to 2021). "The further study of PLCγ2 pathway will provide new targets for the prevention and therapeutic intervention of fungal infection." (PMID 30005593, 2018). "Besides functioning in BCR signaling, PLCγ2 also plays an critical role in the innate immune system as a key component of the downstream signaling pathway for many receptors in response to fungal infection." (PMID 30005593, 2018). "Murine macrophages lacking PLCγ2 are also defective in the pattern recognition receptor for fungal cell walls, dectin-2 signaling in response to fungal infections as highlighted by reduced inflammatory cytokine responses, NF-κB and MAPK signaling, ROS, and clearance of fungal infections in vivo." (PMID 34157287, 2021).
gastric MALT lymphomas (2 papers, 2016 to 2019). "Phospholipase C gamma 2 (PLCG2) plays key roles in B-cell survival and proliferation, and a mutation in the PLCG2 gene can protect mice from Helicobacter-induced gastric mucosa-associated lymphoid tissue lymphoma." (PMID 31993418, 2019). "We used BALB/c mice with a gain-of-function mutation in the Plcg2 gene (Ali5) to analyze its role in the development of gastric MALT lymphoma." (PMID 26966907, 2016). "We hypothesized that due to their autoimmune-prone phenotype, mice with the mutated Plcg2 gene were more susceptible to development of gastric MALT lymphomas." (PMID 26966907, 2016). "Although Plcγ2 is normally involved in activation of immune cells, we could show that Plcg2Ali5/+ mice were protected from developing gastric MALT lymphomas after long-term infection with H. felis, most likely as a result of increased numbers of immunosuppressive CD73+ Tregs." (PMID 26966907, 2016).
glioma (2 papers, 2024 to 2025). A benign or malignant brain and spinal cord tumor that arises from glial cells (astrocytes, oligodendrocytes, ependymal cells). "Targeted inhibition of PLCG2 attenuated glioma growth, invasion, and metastasis." (PMID 39494327, 2024).
hypoxic-ischemic encephalopathy (2 papers, 2022 to 2023). "PLCG2 regulates oxidative stress in hypoxic-ischemic encephalopathy, and activated PLCG2 signaling to attenuate oxidative stress-induced neuronal degeneration and apoptosis." (PMID 36873932, 2023). "Activation of Csf1r/Plcg2 signaling pathway attenuates inflammation and thus regulates the pathogenesis of hypoxic-ischemic encephalopathy." (PMID 35346355, 2022).
inflammatory bowel disease (2 papers, 2020 to 2024). A spectrum of small and large bowel inflammatory diseases of unknown etiology. "In humans, point mutations of PLCG2 can lead to autoimmune inflammation, resulting in arthralgia and inflammatory bowel disease, suggesting that point mutations of PLCG2 are an essential mechanism for inducing immune inflammation." (PMID 38223749, 2024).
lung adenocarcinoma (2 papers, 2021 to 2023). A carcinoma that arises from the lung and is characterized by the presence of malignant glandular epithelial cells. "In addition, the expression analysis from the CPTAC samples in UALCAN online databases also showed a higher expression of PLCG2 in lung adenocarcinoma (LUAD)." (PMID 37031207, 2023). "For example, Xu and Chen utilized a six AG-based pattern (APOC3, EPOR, H2AFX, MXD1, PLCG2, and YWHAZ) to structure a risk model that could efficiently stratify the existing cases in high- and low-risk groups in terms of OS in lung adenocarcinoma (LUAD)." (PMID 34976839, 2021).
malaria (2 papers, 2019 to 2025). Malaria is a serious and sometimes fatal disease caused by a parasite that commonly infects a certain type of mosquito which feeds on humans. "As compared to classical MBCs, higher basal levels of phosphorylated BCR signaling molecules, most notably Syk and PLCγ2, were observed in malaria-associated atypical MBCs similar to the observation for CD21low B cells from CVID patients." (PMID 31068937, 2019). "Compared with those in the control group, the expression levels of key node proteins of Fcγ R-mediated phagocytosis, including SYK, PI3K, PLCγ2, p-MARCKS, CDC42, and RAC, in the spleen samples of the malaria group decreased significantly (P< 0.01 or< 0.05)." (PMID 41425569, 2025). "Compared with those in the malaria group, the expression levels of proteins SYK, PI3K, PLCγ2, and RAC in the spleens of mice in the ZF-CQ group increased significantly (P< 0.01 or< 0.05), and the expression levels of proteins p-MARCKS and CDC42 showed an upward trend." (PMID 41425569, 2025).